BRCA2 (BRCA2 DNA repair associated)
Diseases named in the same sentence as BRCA2 in open-access papers (continued):
Sharing a sentence is not in itself a finding about the gene and the disease.
cancer (continued). "From variant analysis of 46 cancer susceptibility genes, we identified 7 pathogenic and likely pathogenic germline variants in 7 genes in 7 (8%) of the 87 patients, namely, MUTYH, RET, TSC2, BRCA1, BRCA2, ERCC2 and HRAS." (PMID 29684080, 2018). "Conversely, immunoprecipitation of BRCA2 from EUFA423 B2 (lanes 1–3) or EUFA423 (lanes 4–6) cell extracts demonstrates that full-length BRCA2, as well as the cancer-associated BRCA29000insA truncated mutant protein, interact with RNAPII detected by an antibody against its CTD." (PMID 29386125, 2018). "Consistently, amplification of the EMSY gene has been proposed to mimic the BRCA2-mutant phenotype which might be a mechanism of BRCA2 pathway inactivation and consequent sensitization of cancer cells to DNA damaging drugs." (PMID 29707144, 2018). "Inherited variation in the BRCA1 and BRCA2 genes can indicate genetic predisposition to breast, ovarian, and other cancers, but a large proportion of observed variants are not disease associated ("pathogenic")." (PMID 30586411, 2018). "What has emerged is that whereas some germline variants confer high risk for cancer due to disruption of gene function, many BRCA1 and BRCA2 variants identified during routine genetic testing are determined to have little or no clinical significance with respect to cancer risk." (PMID 30586411, 2018). "The mechanism underlying the development of cancer due to loss of BRCA1 and BRCA2 has been explained by the ‘caretaker and gatekeeper’ hypothesis." (PMID 29416040, 2018). "Other factors may contribute for the GC cases observed in our BRCA2 carriers, since Portugal has a high incidence and mortality of this cancer." (PMID 29456621, 2018). "Known risk factors for these hormonally dependent cancers are not overlapping, with the exception of rare individuals harboring susceptibility alleles in the BRCA2 (and less commonly BRCA1) gene." (PMID 28946846, 2017). "Also, germline BRCA1/2 mutations were an independent predictive factor for the development of RDR, while patients harboring germline BRCA1 mutant tumors had worse outcomes to PARP inhibitors relative to patients with BRCA2 mutant cancers." (PMID 29262651, 2017). "In our hospital cohort, we detected one recurrent BRCA1 mutation (p.R1203X (c.3607C>T)) in one double cancer patient and in one OC patient without a family history, and the BRCA2 p.S1722fs (c.5164_5165 delAG) mutation was detected in two OC patients." (PMID 28961279, 2017). "Taken together, these data confirm PARP-inhibitor-induced multinucleation in BRCA1- or BRCA2-deficient tumour cells, and suggest that failed mitosis may contribute to the cytotoxicity of PARP inhibition in these cancer cells." (PMID 28714471, 2017). "At which extend a cancer predisposing protein truncating mutation (e.g., in BRCA1 or BRCA2) will impair DNA surveillance complexes can also depend on the presence of particular polymorphic forms in other proteins participating in the same complexes (called modifier genes in this case)." (PMID 28649653, 2017).
cancer (continued). "In the case of ovarian cancer, which is the 7th most common cancer in women world-wide with an estimated age-standardised rate (ASR) of 6.3 per 100 000, it is known that germ line mutations in BRCA1 and BRCA2 increase the cancer risk in affected families dramatically." (PMID 28759630, 2017). "Inhibition of PARP is an effective strategy for suppressing cancers with BRCA1 and BRCA2 mutations." (PMID 27147578, 2016). "DNA repair defects due to detrimental BRCA2-mutations confer increased susceptibility towards DNA interstrand-crosslinking (ICL) agents and define patient subpopulations for individualized genotype-based cancer therapy." (PMID 26843614, 2016). "The absence of HR, which is a characteristic of BRCA1/BRCA2 deficient cancer cells, activates error-prone DSB mechanisms like non-homologous end joining (NHEJ) and results in genomic instability." (PMID 27532258, 2016). "In future research, it will be interesting to determine whether the CES genes act synergistically with other genes involved in genome maintenance, such as BRCA1 and BRCA2 (refs 71, 72), to promote cancer progression." (PMID 27577169, 2016). "The only target gene that was not mutated in CRISPR/Cas9-induced cancers was Brca2, despite the fact the Brca2 sgRNAs are functional and were shown to mediate indel formation with similar efficiencies to other sgRNAs in vitro." (PMID 26916719, 2016). "Therefore, a multiplicative model of cancer risk for BRCA1 and BRCA2 is inconsistent with the current observations." (PMID 27836010, 2016). "In concordance, inhibition of RAD52 DNA binding activity by small peptide aptamer exerted synthetic lethality in BRCA1 and BRCA2 mutated cancer cells and shRNA-mediated downregulation of RAD52 is lethal in tumor cell lines carrying BRCA2 inactivating mutations." (PMID 26784987, 2016). "An important question when inhibiting BRCA2 in the context of olaparib treatment is whether non-cancer cells are affected to the same degree as tumor cells." (PMID 26959114, 2016). "Our study thus defines a new genetic subpopulation of cancers susceptible towards TRAIL-R-targeting compounds, which could facilitate novel therapeutic approaches for patients with BRCA2-deficient tumors." (PMID 26843614, 2016). "Our findings add an important new angle to this observation, showing that oncogenes can induce R-loops, which suggests that increased R-loop levels might also be common in cancer cells that are proficient in BRCA1 or BRCA2." (PMID 27725641, 2016). "Mutations in BRCA2 and other proteins that control RAD51 activity are associated with human cancer." (PMID 25539919, 2015). "Cancers without BRCA1 or BRCA2 loss but with accumulation of similar genomic scars also show increased sensitivity to platinum-based chemotherapy." (PMID 26015868, 2015). "Autoantibody frequency to PARP1, BRCA1, and BRCA2 in cancer varied from 0% to 50%." (PMID 25865228, 2015). "The genomic instability of BRCA1- and BRCA2-defective cells can be exploited for cancer therapy." (PMID 25769025, 2015). "None of these patients’ cancers had alterations in chromatin remodeling genes, and only one of the nine cancers contained a somatic mutation in a DNA-damage-response pathway gene, BRCA2 (data not shown)." (PMID 25871911, 2015). "It is worth noting that although LOH in cases with BRCA1 and BRCA2 truncations mutations were largely restricted to OV and BRCA, the majority of LOH truncations in other genes (for example, ATM, PALB2, BAP1, FANCM) were found across cancer types." (PMID 26689913, 2015).
cancer (continued). "Whereas homozygous inactivation of HR genes is usually embryonic lethal, heterozygous inactivation of for instance BRCA1 and BRCA2 does not interfere with cellular viability and rather predisposes to cancer, including breast and ovarian cancer." (PMID 25852742, 2015). "It should be noted that, even in the case of highly penetrant cancer predisposition genes, such as BRCA1 and BRCA2, population-based studies have revealed that about half of all heterozygous mutation carriers with incident cancers lack a family history of breast or ovarian cancer." (PMID 26092435, 2015). "Estimates of cancer risk are variable across different studies; nevertheless, two large meta-analyses, resulting from a total of 31 published studies, estimated an OC risk to age 70 of 49% for BRCA1 and 18% for BRCA2 and of 39% for BRCA1 and 11% for BRCA2." (PMID 25136623, 2014). "We hypothesize that SNPs in PARP1 and other members of BER may be associated with cancer risk in BRCA1 and BRCA2 mutation carriers." (PMID 24698998, 2014). "This study aimed to determine whether telomere length (TL) is a marker of cancer risk or genetic status amongst two cohorts of BRCA1 and BRCA2 mutation carriers and controls." (PMID 24489760, 2014). "Based on the interaction of synthetic lethality that has been described between PARP1 and both BRCA1 and BRCA2, we hypothesize that this and other genes involved in the BER pathway could potentially be associated with cancer risk in BRCA1/2 mutation carriers." (PMID 24698998, 2014). "It has been shown that BRCA2-defective cancer cells or treatment of cancer cells with BRCA2 siRNA significantly reduces BRCA2 protein and mRNA expression, leading to tumor radio-sensitization in vitro and in vivo, mainly through the inhibition of homologous recombination repair." (PMID 25481245, 2014). "These possibilities have been previously postulated to explain why some cancers in humans with heterozygous BRCA2 mutation do not develop BRCA2 LOH or promoter methylation." (PMID 24489863, 2014). "Patients with BRCA-associated cancers usually lack wild-type BRCA1 or BRCA2 in tumor cells but normal cells retain a single wild-type copy of the gene." (PMID 25136623, 2014). "Almost all of the BRCA1 and BRCA2 variants observed in our cohort are unlikely to have strong effects on cancer susceptibility." (PMID 24728327, 2014). "Germline carriers of deleterious BRCA2 mutations that commonly truncate the encoded protein exhibit an increased lifetime risk of developing PDAC, in addition to their well‐known predisposition to cancers of the breast and ovary." (PMID 24268522, 2014). "Neither Brca2Tr/WT mice, nor strains heterozygous for other Brca2 truncation mutants, exhibit cancer predisposition." (PMID 24268522, 2014). "There is only one study from the CIMBA consortium which has evaluated the role of three of the most studied SNPs in the XRCC1 gene, c.-77C>T (rs3213245) p.Arg280His (rs25489) and p.Gln399Arg (rs25487), ruling out associations of these variants with cancer risk in BRCA1 and BRCA2 mutation carriers." (PMID 24698998, 2014). "Direct inhibition of BRCA1 and BRCA2 in tumors is generally problematic due to the wide expression of these proteins in most tissues and inhibition may lead to other issues, including cancer development in healthy tissue." (PMID 24795863, 2014). "A cancer familial history was present in 31.4% of the unrelated patients, from them 43.7% were carriers for germline mutation (37.5% in BRCA1 and in 6.2% in the BRCA2 genes)." (PMID 23469205, 2013).
cancer (continued). "Although there is considerable information on the molecular interactions of PARP and BRCA1- and BRCA2-deficient cancers, very little is known of the PARP inhibition effect upon cancers proficient in DNA double-strand break repair after ionizing radiation or after stalled replication forks." (PMID 23396107, 2013). "However, the genome of BRCA2-defective cancer cells is highly unstable and some cancers gain resistance to PARP inhibitors through de novo mutations." (PMID 22325354, 2012). "The distinct histological features of these tumours correlate with distinct molecular genetic profiles, however, in female cancer a correlation with BRCA2 mutation has not been described or suggested." (PMID 23146383, 2012). "We tested the applicability of the evaluated tNGS method on E. coli, as a simple model to optimize the process, and human genomic samples in three experimental stages of increasing scope and complexity, culminating in a SNP concordance evaluation for the BRCA1 and BRCA2 cancer genes." (PMID 22913592, 2012). "Another study on cancer patients in northeastern India also found that the subjects with family history of cancer were more likely to develop ESCC if they were BQ users and germ line mutations in the DNA repair gene, BRCA2, played a role in this familial aggregation of ESCC." (PMID 22912735, 2012). "The distinctive profile of small deletions with rearrangement breakpoints showing overlapping microhomology in BRCA1 and BRCA2 mutant cancers is therefore compatible with these processes being defective and of NHEJ or other error-prone mechanisms of DSB repair acting in their place." (PMID 22608084, 2012). "The five most significant BioCarta pathways were first multivalent nuclear factor, FAS signaling pathway (CD95), p38 MAPK signaling pathway, control of skeletal myogenesis by HDAC and calcium/calmodulin-dependent kinase (CaMK), role of BRCA1, BRCA2, and ATR in cancer susceptibility." (PMID 21836821, 2011). "This synthetic lethality interaction led us to hypothesise that SNPs in genes participating in this pathway could be potential modifiers of cancer risk in BRCA1 and BRCA2 mutation carriers." (PMID 21427728, 2011). "We have detected aberrant methylation in five cancer-related CpGIs, that is estrogen receptor-α [ESR1 (+244bp)], O6-methylguanine-DNA methyltransferase [MGMT (-463bp)], Wilms' Tumor-1 [WT-1 (-146bp)], Breast Cancer 2 [BRCA2 (+138bp)] and Hermen Antigen [CD44 (+28bp)]." (PMID 22011321, 2011). "Interestingly, anti cancer treatments that involve BRCA2 and telomerase individually are currently being explored." (PMID 22152194, 2011). "This suggests that the entire molecular network of BRCA2 is critical for cancer prevention, and defects of other proteins related to BRCA2 may contribute to additional tumors." (PMID 21966279, 2011). "Parallel to FA, we hypothesized that germline mutations or common variants in MORF4L1 may confer moderate/low risk of BrCa and/or modify cancer risk among BRCA1 and/or BRCA2 mutation carriers." (PMID 21466675, 2011). "This may mean that the tested family member developed cancer by chance, or there is a very small chance that a mutation is present in BRCA1 or BRCA2 but was missed due to limitations in current technology." (PMID 20180951, 2010).
cancer (continued). "Interestingly, a recent study found that ER+ cancers which develop in BRCA2 carriers are of higher grade than age matched ER+ sporadic cancers." (PMID 21080930, 2010). "Further, Antoniou and colleagues have shown that modifying loci associated with BRCA2 cancers, but not with BRCA1 carriers, parallel those associated with ER-positive disease in the general population." (PMID 20482762, 2010). "There is currently great hope that these PARP inhibitors may represent a great opportunity to improve the therapy for BRCA1 and BRCA2 cancer patients." (PMID 21054854, 2010). "Based on the available literature, it is deemed appropriate to acknowledge that the clinical management of cancer risk in BRCA1 and BRCA2 mutation carriers is a rather complex and stressful task, which should consider individual patients' expectations and preferences." (PMID 20961453, 2010). "Interestingly, the presence of these two alterations in carcinomas appears to be more frequent than just one occurring by chance, considering the low frequency of PALB2 and BRCA2 mutations in control populations." (PMID 20122277, 2010). "Cancers in BRCA1 and BRCA2 mutation carriers have substantial difference between them." (PMID 19226467, 2009). "This suggests that the entire molecular pathway of BRCA2 are critical for cancer prevention, and other proteins related to BRCA2 may contribute to additional tumors." (PMID 19653894, 2009). "As many cancer-related genes have been linked to the development of polyploidy, for example MYC, APC, Pim-1, BRCA2, and Aurora-A, our model may reflect an actual pathway for tumor initiation." (PMID 18596907, 2008). "Cancer risks associated with BRCA1 and BRCA2 mutations have been well documented, but are varied." (PMID 19102775, 2008). "BRCA2 N372H (rs144848), XRCC1 R399Q (rs25487), and OGG1 S326C (rs1052133) are three SNPs in DNA repair genes consistently associated with cancer risk, supported by thirty studies." (PMID 18547414, 2008). "Abnormalities in BRCA1 and BRCA2 in cancer have been reviewed elsewhere." (PMID 18047734, 2007). "BRCA2 gene expression, owing to its functional relevance, is tightly regulated by several known and unknown factors, which in turn could be candidates responsible for the deregulated expression of BRCA2, thus leading to cancer." (PMID 17945002, 2007). "If so, then agents that upregulate BRCA1 and BRCA2 in mammary epithelial cells may prevent cancer development." (PMID 16434996, 2006). "For the BRCA1 (BRCA2) group, the probability that CE MRI and mammography combined would be cost-effective would be 0.57 (0.82) and 0.71 (0.96) for a decision maker's willingness to pay per cancer detected of £20 000 and £30 000 respectively." (PMID 17016484, 2006). "BRCA1 could be characterized as having a basal phenotype, ER-negative and HER2-negative, with up-regulation of cyclin A and caspase 3, but downregulation of cyclin D1 and D3, CDKIs (p16, p21, p27), and BCL2, the opposite phenotype from most BRCA2 carcinomas." (PMID 16595007, 2006). "Women with the BRCA2 variant were more likely to have bilateral cancer (5% versus 3%) or multifocal cancer (30% versus 23%) but these differences were not statistically significant." (PMID 16280055, 2005). "BRCA2 methylation was found only in one patient with stage IC only cancer." (PMID 15574200, 2004). "It is interesting to see that no occult carcinomas were found in our remaining group of women with either a BRCA2 mutation or non-informative DNA test results." (PMID 15083174, 2004). "Our results suggest that carriers of a BRCA1 germline mutation have a substantial higher risk of occult carcinomas compared to BRCA2 carriers or non-informative test results." (PMID 15083174, 2004).